S100B (S100 calcium binding protein B)
Diseases named in the same sentence as S100B in open-access papers (continued):
Sharing a sentence is not in itself a finding about the gene and the disease.
Stroke (continued). "S100B levels are predictive of complications after stroke-induced ischemic injury." (PMID 39001884, 2024). "In addition, S100-β at 48 h of stroke onset was predicted to be higher than serum NSE on admission (P = 0.025)." (PMID 39669377, 2024). "Interestingly, the expression of S100B is regulated by miR-602, changes in expression of both miR-602 and S100B in have been observed in stroke patients." (PMID 39001884, 2024). "In addition, patients with END had the highest serum NSE and S100-β levels on admission and at 48 h of stroke onset, respectively." (PMID 39669377, 2024). "Both GFAP and S-100B show time-dependent increases post-stroke." (PMID 39459548, 2024). "Five studies showed higher S100B levels in AIS patients compared to stroke mimics." (PMID 39091977, 2024). "Serum NSE on admission and S100-β at 48 h of stroke onset may serve as biomarkers of short-term clinical outcome in patients with AIS." (PMID 39669377, 2024). "S100b is widely used in emergency medicine due to its high positive predictive value in cases of brain injury, showing a correlation with the severity of post-traumatic neurological deficit as well as with the infarct volume after stroke." (PMID 37719764, 2023). "In recent years, there has been increasing interest in the identification and validation of brain biomarkers in clinical routine, and the utility of blood S100B as a brain injury marker has been documented in multiple contexts such as with circulatory arrest, stroke and TBI." (PMID 37047574, 2023). "Despite that, S100B is not deemed a reliable biomarker to predict hemorrhagic transformation in thrombolyzed patients with stroke in clinical practice, mainly because its low diagnostic accuracy." (PMID 37474905, 2023). "Overall, the combination of S100B protein and IL-1 beta holds potential as valuable biomarkers for early prediction of malignant stroke edema, which could have significant implications for clinical decision-making and patient outcomes." (PMID 37752283, 2023). "Many studies have related S100B to a diversity of psychiatric and neurodegenerative diseases, such as Alzheimer’s disease, Down’s syndrome, schizophrenia, and Tourette’s syndrome, in addition to the known correlation between S100B and trauma and stroke." (PMID 37474905, 2023). "However, further studies are needed to establish the predictive values of serum S100B levels for disease burden and clinical outcomes in stroke patients." (PMID 37342100, 2023). "S100B serum levels, however, seem to be able to predict stroke complications." (PMID 37474905, 2023). "S100B is the most extensively studied protein in the diagnosis and treatment of various conditions of CNS, and it can be used as a peripheral marker of brain damage, such as traumatic brain injury and stroke." (PMID 37006533, 2023). "Additionally, biomarkers such as S100B, glialfibrillary acidic protein, and neuron-specific enolase have shown promise inassessing stroke severity and prognosis." (PMID 39430040, 2023). "Finally, previous studies have found that GFAP and S100B correlated with stroke severity and outcome." (PMID 36176549, 2022). "S100b serum levels are known to be higher in stroke cases with larger lesion volumes." (PMID 36756347, 2022). "Also, as S100b levels can increase in cases of pre-stroke trauma or very recent surgery and this should be considered in further studies." (PMID 36756347, 2022). "Many studies have showed that the levels of S100B protein could gradually rise within three days after stroke onset." (PMID 35866730, 2022). "Elevated levels of S100b protein in biological fluids are observed in several neurological disorders, such as multiple sclerosis, Alzheimer's disease, Parkinson's disease, amyotrophic lateral sclerosis and stroke." (PMID 36756347, 2022).
Stroke (continued). "They demonstrated that their model successfully mimicked the ischaemic response as evidenced by the upregulated mRNA expressions of the key markers for stroke, S100B, IL-1β and MBP and additionally substantiate the role of transient cell-substrate interactions herein." (PMID 35806146, 2022). "If we take this finding into account, we could suggest that to determine the relations between long-term neurological survival rate and S100B protein serum levels, the blood sampling could be done 48-72 hours after stroke onset." (PMID 35866730, 2022). "Another study reported that a plasma S100β concentration was lower than 1.364 pg/ml within 6 h after symptom onset could predict the development of epilepsy after a hyperacute stroke event (include IS and HS)." (PMID 34168606, 2021). "The same team have also demonstrated, in a cohort of 915 stroke patients, that just S100B and sRAGE, could distinguish between IS and ICH with an AUC of 0.76 for blood samples obtained within 3 h after symptom onset." (PMID 33633673, 2021). "Serum S100B concentration measured 24 h after symptom onset is significantly higher in stroke patients (posterior circulation IS or infratentorial ICH, no distinction was made in the analysis) than in controls or in patients with vertigo from non-vascular causes." (PMID 33633673, 2021). "S100B was elevated in stroke groups compared to TIA and control." (PMID 33115334, 2021). "In order to find a reliable and specific biomarker that can help predict post-operative neurological results in patients who suffered stroke, we conducted a prospective observational cohort study and investigated changes in serum S100β, NSE, and NFL levels after surgery." (PMID 34859071, 2021). "In this context, new miniaturized biosensing POC prototypes are under development for fast multiplex monitoring of different biochemical and genetic pathways potentially associated with stroke (e.g., MMP9, TNF-α, IL6, S100B, GFAP, microRNA) in minimally invasive blood samples." (PMID 34440560, 2021). "However, in addition to prolonged and delayed release into the blood after stroke, S100B levels are also increased in other neurological pathologies such as traumatic brain injuries and extracranial malignancies." (PMID 33633673, 2021). "In these cases, an increase in concentration of S100β protein may serve as an early warning signal before it becomes visible in the CT image (if available) in the early phase of stroke." (PMID 31701356, 2020). "Furthermore, electro-acupuncture stimulation to Fengfu (GV 16) was found to be neuroprotective for patients with OD after stroke by stimulating the downregulation of S100β-mediated neurotoxins." (PMID 30898173, 2019). "The peak level of S-100B occurs on the third day following a stroke." (PMID 31847312, 2019). "S-100B could be considered a biomarker of brain damage in stroke, circulatory arrest and traumatic brain injury." (PMID 31263455, 2019). "Thus, the concentration of S100β proteins increases significantly at the onset of IS and correlates with infarct volume, stroke severity and functional outcome." (PMID 30069254, 2018). "S100B protein is a sensitive biomarker of brain injury following stroke." (PMID 28761630, 2017). "The level of serum S100B in ischemic stroke implied a worse outcome secondary to the stroke." (PMID 29379499, 2017). "S100B is a prototype biomarker for brain injuries including trauma and stroke." (PMID 25986246, 2015). "S100B is expressed and released by astro and oligodendrocytes in response to glial activation or injury and was recently studied as a potential serum biomarker for traumatic brain injury, stroke, depression, and blood brain barrier injury." (PMID 25986246, 2015). "For determination if initial levels (at 6 h) of IL-10, IL-6 and CRP are independently associated with infection in ischemic stroke patients, we performed a binary logistic regression analysis that was adjusted for NIHSS on admission, stroke etiology, and peak levels of S100B." (PMID 25613713, 2015).
Stroke (continued). "Indeed, a plasmatic S100β level >1.03 μg/l at 24 hours after the onset of stroke predicts malignant infarction in patients with proximal middle cerebral artery occlusion, with a sensitivity of 94% and a specificity of 83%." (PMID 25029344, 2014). "A recent review described the serum S100β temporal profile after stroke onset." (PMID 25029344, 2014). "In manifest stroke serum S100B levels described a decelerated increase compared with GFAP." (PMID 23509668, 2013). "The concentration of S100β is known to be the highest 72 hours after the onset of stroke." (PMID 22206485, 2011). "S100B has been shown to increase in cerebrospinal fluid (CSF) and serum after various neurological diseases (for example, trauma, stroke, inflammation, bacterial and viral meningitis) and it has been postulated that S100B could serve as a serum marker for brain damage." (PMID 40076533, 2025). "Additionally, a specificity test was performed using S100b, another common stroke biomarker." (PMID 40277577, 2025). "Therefore, serum S100β levels may be used as an early biomarker to predict outcomes in patients with stroke." (PMID 39358745, 2024). "The association of S100β levels and HT was not significant in either stroke lateralization group." (PMID 39358745, 2024). "In particular, S100b can up-regulate macrophage production of pro-inflammatory cytokines and worsen severity of inflammation, therefore, we could hypothesize a similar role also in stroke inflammation." (PMID 36756347, 2022). "Glial proteins such as glial fibrillary acidic protein (GFAP), and S100β, which are both structural astrocytic proteins, are two very promising blood biomarkers that could be indicative of stroke in patients presenting with symptoms of acute neurological dysfunction." (PMID 35813155, 2022). "Finally, we assessed the relationship between the baseline NIH scale as an indirect measure of the severity of the stroke, the concentration of the S100β in the follow up samples as an indicator of the infarct size, and the outcome of the disease assessed by the modified Rankin scale." (PMID 22206485, 2011). "Following brain damage, as in the case of stroke, when the BBB is disrupted, injured glial cells can release S100B into the bloodstream and urine." (PMID 41598337, 2026). "In this study, we aimed to delineate the effects of mono- and combinatorial pre-treatment upon neurological status and biomarkers, namely protein S100b, GFAP, procalcitonin, and galectin-3, following stroke." (PMID 40863995, 2025). "In the present work, we aimed to delineate the effects of mono- and combinatorial pre-treatment upon neurological status and neurological integrity biomarkers, namely protein S100b, GFAP, procalcitonin, and galectin-3, following a cerebrovascular accident." (PMID 40863995, 2025). "The results of this systematic review, along with findings from existing literature, indicate that S100B, GFAP and NSE hold promise as biomarkers for brain injury in stroke, particularly in individuals with T2DM." (PMID 41150802, 2025). "A key recommendation is to incorporate advanced diagnostic techniques, such as MRI and Transcranial Doppler Ultrasound, to improve the accuracy of stroke detection and validate biomarkers like S100B, GFAP and NSE as non-invasive stroke indicators." (PMID 41296388, 2025). "And the degree of cognitive dysfunction in stroke patients is positively correlated with the expression of NSE and S-100B." (PMID 40832150, 2025). "The concentrations of these biomarkers are increased after stroke and help to determine the severity of brain injury, with NSE being a marker of neuronal death, GFAP for astrocytic injury and S100B for brain cell injury." (PMID 41296388, 2025). "The reviewed studies highlight the potential of S100B and GFAP as significant biomarkers in the prognosis and diagnosis of patients with stroke and their ability of predicting long-term neurological deficits." (PMID 39459548, 2024).
Stroke (continued). "In a study from the USA: NSE, S100B and CKBB in CSF were investigated as predictors of outcome in stroke patients." (PMID 39001884, 2024). "This novel herb-based product improves motor control evaluated using the NIHSS and stroke serum biomarkers, such as MMP-9, VCAM-1, and s100β, in patients who experienced transient ischemic stroke and minor ischemic stroke." (PMID 39599732, 2024). "We further explored the correlation between miR-142-5p expression levels and National Institutes of Health Stroke Scale (NIHSS) scores, NSE, and S100β." (PMID 39669376, 2024). "This review focuses on analyzing the prognostic utility of S100b protein after acute brain injuries (particularly TBI and stroke) that progress to BD." (PMID 39036258, 2024). "A biomarker panel comprised of S100B, and high fatty acid binding protein (H-FABP) was conducted among 111 AIS patients, and 127 stroke mimics." (PMID 39091977, 2024). "HMGB1 levels positively correlated with markers of neural damage like S100B and NSE in stroke patients." (PMID 38708343, 2024). "Subsequently, S100b has been shown to be a promising biomarker for severity stratification and prediction of clinical outcomes in TBI, stroke (ischemic and hemorrhagic), and cardiac arrest." (PMID 39036258, 2024). "Studies have reported promising sensitivity and specificity for S100B in distinguishing between IS and ICH, with notable accuracy in predicting short-term functional outcomes post-stroke." (PMID 39459548, 2024). "Increased levels of S100b can be observed not only in TBI and stroke but also in various other conditions, including brain tumors, CNS infections such as encephalitis and meningitis, and neurological diseases such as multiple sclerosis and epilepsy." (PMID 39036258, 2024). "S100b, part of the DAMP protein family, is released during post‐stroke neuroinflammation, leading to microglial activation and inflammation." (PMID 38041607, 2024). "The integration of S100B and GFAP with existing clinical scales can improve the accuracy and predictive power in assessing stroke outcomes." (PMID 39459548, 2024). "The aim of the present review, therefore, is to analyze and summarize the recent relevant clinical literature on molecular markers of focal hypoxia with particular emphasis on the prognostic role of S100B protein and the GFAP in patients with stroke." (PMID 39459548, 2024). "The only available study to investigate S100B after ATAAD surgery included 88 patients, 15 of whom (17%) suffered a stroke after surgery." (PMID 36747206, 2023). "A study on 32 consecutive patients evaluated changes of S100b and the neuron specific enolase (NSE) levels between the first 6 h, and in the 5 days after stroke." (PMID 37719764, 2023). "Univariate logistics regression analysis showed that right hemisphere, HCY, CRP, NSE, S100β, Anticoagulation, PPI, dysphagia, and SS all had statistically significant correlation with the occurrence of stroke recurrence." (PMID 37051146, 2023). "The stroke cavity is walled off by glial scar tissues; hence it can be traced by using GFAP and/or S100β staining." (PMID 37867250, 2023). "Up-regulation of S100B protein synthesis and leakage of S100B from damaged astrocytes that express GFAP in the glial scar can be induced by acute brain injury (e.g., stroke or TBI)." (PMID 36986535, 2023). "After stroke, tau, NFL, GFAp and S100B increased in a time dependent manner, while NSE remained constant over time." (PMID 33723754, 2022). "But for the two patients who had a stroke and one patient who died, the serum concentrations of GFAP and S100B increased continuously even at the 30-day follow-up after CAS." (PMID 34381130, 2021). "S100B, NSE, GFAP, and MAPT have previously been used as markers of neuronal damage, such as in stroke, traumatic brain injury, and aneurysmal SAH." (PMID 32978732, 2021).
Stroke (continued). "The combination of S100B, B-type neurotrophic growth factor (BNGF), von Willebrand factor (vWF), MMP-9, and monocyte chemotactic protein-1 (MCP-1) provided diagnosis of stroke within 12 h after symptom onset with a 91% sensitivity and a 97% specificity." (PMID 33633673, 2021). "One day post stroke, only a few S100β+ cells were observed in peri-ischemic areas after 90-min t-MCAO and p-MCAO, but an abundance were observed at 56 d post stroke in both models." (PMID 32492968, 2020). "The neurobiochemical marker, S100B, has a pathognomonic role in the diagnosis of a broad spectrum of brain damage including traumatic brain injury (TBI), brain tumor, and stroke." (PMID 28761630, 2017). "S100B, NSE, and GFAP are detectable in the blood early after traumatic brain injury or stroke; however, their half-lives are estimated between 30 minutes and 48 hours." (PMID 28605426, 2017). "The “Triage® Stroke Panel”, a biochemical multimarker assay, detects Brain Natriuretic Peptide (BNP), D-Dimers (DD), Matrix-Metalloproteinase-9 (MMP-9), and S100β protein generating a Multimarker index of these values (MMX)." (PMID 27247610, 2016). "In stroke patients ∆FKN between 6 h and 3 d inversely correlated with S100B at 24 h (r = -0.441, P = 0.001)." (PMID 24722201, 2014). "Increased levels of serum and cerebrospinal fluid (CSF) S100B have been shown in patients suffering subarachnoid hemorrhage (SAH), severe head injury and stroke." (PMID 23761779, 2013). "The "Triage® Stroke Panel", a biochemical multimarker assay, detects Brain Natriuretic Peptide (BNP), D-Dimers (DD), Matrix-Metalloproteinase-9 (MMP-9), and S100B protein and promptly generates a Multimarkerindex of these values (MMX)." (PMID 22400994, 2012). "H-FABP, IL-1ra, IL-8, S100β, CRP and Troponin I concentrations were also significantly increased whereas MMP3 and E-selectin concentrations showed a reduction in stroke patients compared to controls (0.001<p<0.05)." (PMID 23028472, 2012). "There are some biological markers that have been studied as predictors of the type of stroke, including GFAP, NMDA, S100B, and Apo C–III." (PMID 21776296, 2011). "S100B has previously been found to be correlated with CRP in subjects with acute ischaemic stoke at 12, 24 and 72 hours after stroke, after controlling for gender, age and leukocyte count." (PMID 21034449, 2010). "The evidence indicates distinct prognostic patterns: biomarkers of inflammation (e.g., TNF-α, IL-6, IL-1β) and neuronal or glial damage (e.g., S100B, GFAP, NSE, NfL) tend to correlate with less favorable outcomes, especially when measured in the acute phase of a stroke." (PMID 41598337, 2026). "Similarly to S-100B, the levels of NSE are accepted as a marker of the severity of brain damage in stroke patients, including those with diabetes, since the damaged BBB allows NSE to leak out into the bloodstream." (PMID 41150802, 2025). "The exact role of biomarkers S100B, GFAP and NSE in diagnosing stroke is still being defined." (PMID 41150802, 2025). "This novel herb-based product improves motor control as evaluated using the National Institutes of Health Stroke Score (NIHSS); level of post-stroke disability; and stroke serum biomarkers, such as MMP-9, VCAM-1, and s100β, in patients who experience transient ischemic and minor ischemic stroke." (PMID 39599732, 2024). "Analysis of variance did not reveal any statistically significant differences in the mean levels of S100B between various subtypes of ischemic stroke—LAA, SAO, CE, and SUC (stroke of undetermined etiology), with the p-values of 0.911, 0.369, 0.262, and 0.693, respectively." (PMID 38248781, 2024). "Further, we explored the heterogeneity in stroke lateralization (dominant, non-dominant, and both hemispheres) of S100β in HT." (PMID 39358745, 2024).